BRAF (B-Raf proto-oncogene, serine/threonine kinase)
Diseases named in the same sentence as BRAF in open-access papers (continued):
Sharing a sentence is not in itself a finding about the gene and the disease.
melanoma (continued). "Extensive research has consistently demonstrated that immune checkpoint inhibitors and BRAF/MEK inhibitors significantly improve survival rates in patients with advanced melanoma, including stages III and IV." (PMID 39272923, 2024). "ORR, PFS, and OS were compared between patients diagnosed with advanced melanoma and treated with first-line IT or BRAF/MEKi." (PMID 38450188, 2024). "In the case of vemurafenib for malignant melanoma, v-raf murine sarcoma viral oncogene homolog B (BRAF) various V600 mutants have been used to examine the inhibitory effects on kinase activity and phosphorylation." (PMID 38167464, 2024). "Take melanoma as another model where BRAFV600E-induced BRAF/MAPK activation is also the most dramatic carcinogenic mutation, we found knock-down of USP15 resulted in significant TBX3 reduction." (PMID 38750011, 2024). "The area percentage of SNAI1-positive cells showed a significantly higher area percentage score in BRAF+ and BRAF− melanoma samples than in dysplastic nevus (p < 0.01) and melanoma in situ samples (p < 0.0001)." (PMID 39273022, 2024). "To further refine the 3D model and evaluate the long-term effects, we embedded BRAF WT melanoma 3D spheroids in a collagen I matrix before treatment and monitored them over time." (PMID 38263136, 2024). "Vemurafenib and dabrafenib, two BRAF inhibitors, exhibit rapid and substantial efficacy in shrinking tumors in melanoma sufferers." (PMID 39420203, 2024). "BRAF, NRAS, and C-KIT mutations are, nevertheless, often less common in DM than in other forms of melanoma." (PMID 39872575, 2024). "We delve into the role of the BRAF gene in various cancer types such as melanoma, non-small-cell lung cancer, colorectal cancer, and thyroid cancer." (PMID 38539548, 2024). "Different approaches to combining BRAF-targeted therapy and ICIs have been examined in the setting of advanced melanoma." (PMID 38907159, 2024). "Although personalized immunotherapies for BRAF-mutant melanoma present challenges in terms of efficacy and safety, these treatments offer numerous clinical opportunities." (PMID 39336897, 2024). "Similar to the regulatory mechanism under BRAFV600E–induced thyroidal transformation, USP15 is also transcriptionally activated by BRAF/MAPK pathway during melanoma genesis and controls TBX3 stability." (PMID 38750011, 2024). "Clinical responses to these targeted therapies can be profound, with high rates of response and near-complete initial remissions, as exemplified by the BCR-Abl inhibitor imatinib in CML and the BRAF inhibitor vemurafenib in melanoma." (PMID 38778760, 2024). "Adjuvant BRAF/MEK inhibitors and immunotherapy with anti-PD1 have become the standard of care for resected high-risk stage III melanoma patients." (PMID 39727691, 2024). "A total of 199 patients with unresectable stage IV melanoma treated with BRAF and MEK inhibitors (58.8% male) were included in the survival analysis." (PMID 39272837, 2024). "In the clinical setting, it is recommended to initially test for BRAF and NRAS mutations in acral and mucosal melanomas." (PMID 38474231, 2024). "Treatment of BRAF WT melanoma cells with 10 nM trametinib induced G1 arrest at 24 hours and discretely induced apoptotic sub-G1 fractions at 72 hours (5-8%)." (PMID 38263136, 2024). "In vitro research has demonstrated that statins can inhibit melanoma metastasis and augment treatment in BRAF inhibitor-resistant melanomas when used with other drugs." (PMID 38760735, 2024). "A 65-year-old man with Stage IIIb BRAF-mutant melanoma, receiving dabrafenib and trametinib, developed lung and cutaneous sarcoidosis, presenting with symptoms that led to emergency department admission." (PMID 39717410, 2024). "This subsequently led to several Food and Drug Administration (FDA) approvals for BRAF/MEK inhibitors for melanoma, non-small cell lung cancer, anaplastic thyroid cancer, colorectal cancer, histiocytosis neoplasms, and finally, tumor-agnostic indications." (PMID 38203795, 2024).
melanoma (continued). "While melanoma has a well-documented history of genetic mutations, including those in NRAS and BRAF genes among others, epigenetic changes have been increasingly understood to play a pivotal role in the etiology and progression of the disease." (PMID 39199614, 2024). "In BRAF mutant and vemurafenib-resistant cells, the combination therapy of romidepsin and interferon-alpha (IFN-α) effectively reduces melanoma invasiveness, induces mixed apoptotic and necroptotic cell death, and reverses resistance to BRAF inhibitors." (PMID 39654184, 2024). "Trametinib has shown efficacy in multiple types of cancer, such as in BRAF-mutant melanoma and NSCLC patients achieving long-term benefit." (PMID 38643157, 2024). "Combining PD-1 antibodies with targeted agents is now FDA approved for the treatment of advanced melanoma (BRAF/MEK inhibition) and gastric cancer (anti-HER2)." (PMID 39066855, 2024). "Recently, there have been significant advancements in therapies for treating stage III and IV melanomas, including targeting molecular pathways using BRAF and MEK inhibitors or immune checkpoint inhibitors, such as PD-1, CTLA-4, or LAG-3 inhibitors." (PMID 38927967, 2024). "Regarding melanoma therapy resistance, beyond BRAF and NRAS, other pivotal genes come to the forefront." (PMID 39582535, 2024). "ER stress has previously been shown to contribute to the drug-tolerant state in BRAF-mutant melanoma, further supporting its role in Ca2+ dysregulation." (PMID 39001489, 2024). "We found that using dabrafenib to inhibit the overactive BRAF that produces abnormal MAPK signaling profoundly modifies tumor metabolomics in melanoma phenotypes with high BRAF dependence." (PMID 38254853, 2024). "We performed a CRISPR-Cas9 loss-of-function screening to identify genes whose ablation can attenuate vemurafenib resistance in the BRAF V600E mutant A375 melanoma model." (PMID 38965534, 2024). "In melanoma, tumors resistant to BRAF inhibitors show a strong activation of Rho/ROCK signaling, which is linked to increased dedifferentiation." (PMID 39273383, 2024). "The search terms “melanoma”, “mutation”, “surgery”, and “metastatic melanoma” and specific gene names (TMB, BRAF, NRAS, EGFR, c-KIT, MITF, etc.)were used in combination with the Boolean operators AND or OR." (PMID 38534309, 2024). "MITF silencing has been also performed in two BRAF-wild type melanoma cells, namely SKMEL2 and VMM917 cells." (PMID 38472212, 2024). "Patients suffering from BRAF mutant melanoma have tumor recurrence within merely 7 months of treatment with a potent BRAF inhibitor (BRAFi) like vemurafenib." (PMID 39238805, 2024). "EGFR- or ALK-altered lung cancers and BRAF mutant melanoma are some success stories of personalized cancer treatments." (PMID 38485987, 2024). "When combined, SHP2 seems to have an oncogenic function in melanoma and presents a viable new target for melanoma combination treatment, which includes tumors with NRAS and BRAF mutations." (PMID 38504984, 2024). "At diagnosis, 42 (59%) were men, 30 (42%) had BRAF V600E-mutant melanoma, and 43 (61%) had stage IIIC melanoma." (PMID 39682138, 2024). "Drug-resistance is a crucial obstacle of MAPKi treatment successful in advanced melanomas with BRAF mutant." (PMID 38822350, 2024). "More important, these ligands can act in synergy with MAPKi to more efficiently inhibit cell growth and overcome drug resistance in both BRAF wild-type and mutant melanoma." (PMID 37508519, 2023). "Primary melanoma cells isolated from patient biopsies with the BRAF mutant were first treated with a high concentration of VEM (10 μM) for 1 h, followed by four months of 1 μM VEM treatment." (PMID 36331719, 2023). "BRAF testing is recommended at the time of advanced melanoma diagnosis and is present in approximately 50% of cases, information also confirmed by data from real-world studies." (PMID 36831607, 2023).
melanoma (continued). "In patients with resected stage III BRAF-mutant melanoma, BRAF/MEK-inhibition resulted in a better 12-month RFS than anti-PD-1 in matched patients, but this difference was no longer observed at 18 months." (PMID 36672358, 2023). "The PANTHER overrepresentation test revealed that the Notch signaling and PI3 kinase pathways, which are known to be involved in BRAF or MEK inhibitor resistance in melanoma, were exclusively identified in the list of hits obtained by analyzing v." (PMID 36829149, 2023). "MEK is a protein directly downstream of BRAF, which, in more than 50% of melanoma cases, is constituently active." (PMID 36900136, 2023). "This study demonstrated the effect of combination therapy on melanomas, including those resistant to BRAF inhibitors." (PMID 36844227, 2023). "Although CRAF has been reported to be required for non-V600E BRAF melanoma cell viability through an allosteric conformation mechanism or direct phosphorylation of its activation segment, its function in BRAFV600E melanoma is controversial." (PMID 38111008, 2023). "Our experiments have shown that the combination of daphnetin with the BRAF inhibitor vemurafenib showed additivity with a tendency toward antagonism or an antagonistic interaction in human melanoma cells." (PMID 37371063, 2023). "We provide experimental evidence that the systemic delivery of LNPs carrying oncosuppressor miRNAs strongly potentiates the antitumor efficacy of MAPKi therapy and blunts the development of drug resistance in BRAF-mutant melanoma xenografts." (PMID 36418472, 2023). "Using LND1 cells (a BRAF wt melanoma cell line) they created spheroids, adding PBMCs onto them to study the trafficking towards the tumor of these cells." (PMID 36831417, 2023). "Melanoma tumors develop BRAFi resistance through a rewiring of signaling network that circumvents the BRAF blockade to achieve ERK activation." (PMID 37183363, 2023). "In a retrospective study, an overall response rate of 82% was observed in melanoma patients treated with BRAF/MEKi after PD1 failure." (PMID 37093349, 2023). "In TNBC, upregulated MYC inhibits the MondoA-dependent activation of TXNIP to stimulate glycolysis, while in BRAF-mutant melanoma, the MYC-induced downregulation of the MondoA-TXNIP axis leads to vemurafenib resistance." (PMID 37443779, 2023). "In another study of melanoma resistant to a BRAF inhibitor, vemurafenib, resistant cells were more sensitive to glutaminase inhibitors than were their sensitive counterparts both in vitro and in vivo." (PMID 37779896, 2023). "Increased HDAC8 expression led to increased survival of melanoma cells exposed to hypoxia, UV irradiation and after treatment with BRAF-MEKi therapy." (PMID 38030596, 2023). "The combinations of dabrafenib + trametinib, vemurafenib + cobimetinib, and encorafenib + binimetinib have demonstrated efficacy against melanomas with mutations in both the NRAS and BRAF genes, and are shown to improve therapy response and overall PFS." (PMID 37181747, 2023). "In a group of BRAF-treated patients with melanoma, those with PD-L1+ were characterized with the worst prognosis." (PMID 36982460, 2023). "In this work, we explored the strategy of VEGFA/BRAF inhibition in immunocompetent melanoma murine models." (PMID 37183363, 2023). "Trametinib is Food and Drug Administration (FDA) approved for use in combination with dabrafenib for incurable BRAF mutant melanoma or also as a single agent." (PMID 37189730, 2023). "For some end-stage patients suffering from unresectable or metastatic malignant melanoma, integrated treatment with BRAF-targeted and MEK-targeted therapies and the emergence of immunotherapy resulted in a significant improvement in OS7,8." (PMID 37770477, 2023). "In a retrospective analysis of 114 patients with advanced BRAF-mutant melanoma, the median OS was similar in those who had the anti-PD-1 in the first line and those who received BRAF ± MEK inhibitors before the anti-PD-1 (27.5 vs. 40.3 months; p = 0.71)." (PMID 36995534, 2023).
melanoma (continued). "Patient 2 - A 68-year-old man with a history of recurrent BRAF-positive melanoma was diagnosed with disseminated metastatic melanoma recurrence, including a rapidly enlarging left adrenal mass." (PMID 36604647, 2023). "Drugs targeting the RAF/MEK/ERK pathway, which are used for BRAF-mutant melanomas, do little to increase progression-free survival (PFS)." (PMID 36765910, 2023). "Ongoing trials are further investigating sequencing strategies for immunotherapy and targeted therapy in BRAF V600-mutant melanoma to evaluate specific regimens." (PMID 36995534, 2023). "Currently, four genomic subgroups of melanoma have been identified through studies of The Cancer Genome Atlas (TCGA) network: BRAF (B-rapidly accelerated fibrosarcoma), NRAS, NF1, and triple wild type." (PMID 37446286, 2023). "For BRAF mutant colon cancer and melanoma, monotherapy showed limited efficacy, however combination therapy confers a promising therapy approach." (PMID 37808191, 2023). "Another study demonstrated that the TME of BRAF‐mutant melanoma is associated with decreased CD8+ T‐cells and increased B‐cells and CD4+ T‐cells, which is distinct from BRAF wild‐type." (PMID 37584204, 2023). "In BRAF(V600E) melanoma cells, activation of BRAF upregulates glycolysis and suppresses oxidative phosphorylation (OXPHOS)." (PMID 38092752, 2023). "Trials in advanced melanoma revealed that survival was higher with combined BRAF plus MEK inhibition during the first 6 months than with immunotherapy, after which ICIs provided a superior survival benefit." (PMID 36995534, 2023). "BRAF inhibitors used to treat BRAF mutant melanomas are known to promote the accelerated growth of clones harbouring RAS mutations." (PMID 37020004, 2023). "Higher rates of BRAF mutations were reported among MBM compared to primary and extracranial melanoma metastases." (PMID 36983983, 2023). "BRAF inhibition‐induced activation of CAFs stimulates the remodeling of the fibronectin‐rich matrix, consequently contributing to melanoma cell persistence by the reactivation of ERK." (PMID 38045829, 2023). "Targeting this ECM-mediated resistance mechanism using a MT1-MMP inhibitor restored sensitivity to BRAF inhibition in resistant melanoma cells." (PMID 36774337, 2023). "In mice implanted with BRAF-mutant melanoma cells, a different combinatorial method utilizing fisetin and sorafenib (an RAF inhibitor) has recently shown suppression of melanoma cell proliferation, induction of apoptosis, and prevention of tumor growth." (PMID 37565061, 2023). "Supporting this, phenformin enhances the antitumor effects of RAF inhibitors in BRAF V600E melanoma mouse models and has antimelanoma effects even in cell lines resistant to vemurafenib." (PMID 37930123, 2023). "Activating mutations in the oncogenes BRAF and NRAS are the most studied mutations in malignant melanoma." (PMID 38201531, 2023). "This is particularly of interest because BRAF is an important target for FDA-approved small molecule therapy in melanoma." (PMID 37235843, 2023). "Patients with BRAF/+/melanomas had a higher probability of 2-year RFS compared to melanoma BRAF/−/patients at 62.9% (95% CI: 49.4–80%) vs. 57.7% (95% CI: 46.4–71.7%), respectively, p = 0.023." (PMID 37686659, 2023). "Mutations in the PI3K pathway are also frequent mechanisms of adaptation in melanoma in response to the BRAF/MEK inhibition." (PMID 36967525, 2023). "The MEK inhibitor trametinib (first approved by the FDA for use in BRAF V600E melanoma) has been studied in combination across a variety of contexts." (PMID 37380628, 2023). "As RTKs were found associated with resistance to MAPK inhibition, phenotype switch, invasion, metastases and relapses, targeting RTKs was considered of particular importance in melanoma, especially in the non-BRAF mutant melanoma subgroup." (PMID 37215708, 2023).
melanoma (continued). "RYK expression has also been associated with tyrosine kinase inhibitor drug tolerance and resistance in lung cancers, and BRAF inhibitor resistance in melanomas." (PMID 37242509, 2023). "In conclusion, this study sustained the fact that eligible patients with BRAF-mutant melanoma reach clinical benefit with combination immunotherapy as the first line of treatment." (PMID 37404764, 2023). "For example, β-caryophyllene enhanced the antitumor activity of vemurafenib, a BRAF inhibitor, in melanoma cells." (PMID 37515699, 2023). "Taken together, these studies indicated the potential of melatonin in enhancing the efficacy of BRAF-targeting agents in melanoma treatment." (PMID 36649046, 2023). "A CRISPR screen employing ∼18,000 sgRNAs which targeted >700 kb regions surrounding the genes NF1, NF2, and CUL3 was developed to search for resistance to BRAF inhibitor in melanoma." (PMID 37427373, 2023). "CREB3LI has been reported to be activated in drug-resistant cell lines and GLI1 knockout has been shown to increase sensitivity to vemurafenib, an approved melanoma BRAF inhibitor." (PMID 36894939, 2023). "The progression-free survival for BRAF V600E and V600K mutant melanomas was 6.9 and 5.9 months for vemurafenib and 6.3 and 4.5 months in the Phase III trial of dabrafenib." (PMID 37239381, 2023). "It was shown that NRAS mutant melanoma cells can keep their malignant properties after knockout of BRAF and CRAF, being dependent on ARAF to sustain ERK signaling." (PMID 37627277, 2023). "To further understand the effect of TERT overexpression on resistance, we overexpressed TERT in a melanoma cell line expressing a low level of TERT and showed that it was associated with increased resistance to BRAF and MEK inhibition." (PMID 37296851, 2023). "Although the BRAF inhibitor leads to initial tumor regression, most melanoma patients experience recurrence within one year." (PMID 37205993, 2023). "MiR-129-5p expression was increased in a span of 20 days of vemurafenib treatment, but miR-129-5p expression was inhibited in BRAF-resistant melanoma cells with vemurafenib." (PMID 36982460, 2023). "Another recent study integrated mathematical models with clinical data of a cohort of patients with melanoma treated with continuous therapy of BRAF/MEK inhibitors." (PMID 36952376, 2023). "We first generated BAX and BAK (BAX-/-BAK1-/-) knockout and wild-type controls in BRAF(V600E) mutant A375 melanoma cells with CRISPR/Cas9 technology." (PMID 36918588, 2023). "To the best of our knowledge, we have shown for the first time that the combination of ascorbate and PD1 inhibition with J43 is both highly effective and well tolerated in an immunocompetent melanoma mouse model resembling BRAF wild-type melanomas." (PMID 36672190, 2023). "According to the molecular characteristics based on TCGA data for cutaneous melanoma, melanoma can be divided into four subtypes, namely, the BRAF, RAS, NF1 and triple- wild- type subtypes." (PMID 37277447, 2023). "Combined targeted inhibition of mutated BRAF and downstream MEK kinases, or alternatively immune checkpoint inhibition, currently provide good therapeutic options for the systemic treatment of melanoma, offering a long-term survival to ~30% of the patients." (PMID 37495601, 2023). "Targeting the MAPK cascade has emerged as a standard of care for BRAF-mutant melanoma, where combinations of BRAF and MEK inhibitors have proven to be especially effective at prolonging survival." (PMID 37830586, 2023). "This would enable assessment of the effects of long-term ROR2 loss, to further evaluate the extent to which ROR2 is required for the vascular phenotype and VEGF dependency of BRAF mutant melanoma." (PMID 36539575, 2023). "Suppression of the MAPK pathway by targeting BRAF fails because melanoma cells acquire alterations that stimulate the reactivation of MAPK signaling." (PMID 37189846, 2023).